SGK1 (serum/glucocorticoid regulated kinase 1)
Diseases named in the same sentence as SGK1 in open-access papers (continued):
Sharing a sentence is not in itself a finding about the gene and the disease.
Obesity (continued). "It has been proposed that SGK1 promotes obesity by stimulating the Na+ glucose cotransporter SGLT1 (solute carrier family 5 member 1)." (PMID 35456474, 2022). "This is a potentially novel finding in the heart but is an extension of existing literature, which demonstrates obesity-related increases in SGK1 signaling in the aorta, adipose tissue, and hippocampus." (PMID 35998035, 2022). "Our results, however, are in agreement with the previous reports of SGK1 participating in differentiation and function of adipocytes and development of obesity." (PMID 35393773, 2022). "Overall, this study demonstrates the promise of targeting SGK1 in a mouse model of obesity-related AF." (PMID 35998035, 2022). "SGK1 (serum and glucocorticoid-induced protein kinase 1) is regulated by glucocorticoids and is involved in the development of obesity." (PMID 35456474, 2022). "The genes of interest were either cytokines known to be involved in obesity-related inflammation or those thought to lie downstream of either mineralocorticoid or SGK1 signaling." (PMID 35998035, 2022). "Overall, SGK1 inhibition prevents some of the pathologic effects of obesity, making it a necessary signaling pathway and an attractive therapeutic target in this AF model." (PMID 35998035, 2022). "Once again, cardiomyocyte-specific genetic inhibition of SGK1 minimized obesity-induced increases in genes related to inflammation." (PMID 35998035, 2022). "SGK1 signaling therefore presents a unique and attractive therapeutic target given its presumed involvement in multiple obesity-related pathways and its ability to directly modulate cardiac electrophysiology through effects on the INa." (PMID 35998035, 2022). "Here, we demonstrate marked alteration in atrial gene expression brought on by obesity and an obesity-induced upregulation of atrial SGK1 transcription, activation, and activity." (PMID 35998035, 2022). "Together, our data suggest opposing effects of SGK1 activity on obesity-related AF, with SGK1 activation promoting development of AF coincident with increased fibrosis and inflammation, while SGK1 inhibition was protective against these pathologic changes." (PMID 35998035, 2022). "Serum glucocorticoid kinase 1 (SGK1) is a kinase positioned within multiple obesity-related pathways, and prior work has shown a pathologic role of SGK1 signaling in ventricular arrhythmias." (PMID 35998035, 2022). "Our data demonstrated a trend toward an increase in obesity-induced Ccl2 expression, which was prevented by SGK1 genetic inhibition (ANOVA P = 0.05)." (PMID 35998035, 2022). "In summary, this study suggests that targeting of SGK1 should be further investigated for its therapeutic potential in obesity-related AF." (PMID 35998035, 2022). "We demonstrate here that in fact diet-induced obesity does increase both atrial and ventricular SGK1 transcription and signaling." (PMID 35998035, 2022). "Mice expressing a cardiac specific dominant-negative SGK1 were protected from obesity-related AF, through effects on atrial electrophysiology, action potential characteristics, structural remodeling, inflammation, and sodium current." (PMID 35998035, 2022). "We did find, however, inter-atrial differences in action potential characteristics and impulse propagation that were brought on by obesity but reversed with SGK1 inhibition." (PMID 35998035, 2022). "Given the known role of SGK1 in electrical/structural remodeling, we sought to investigate the role of SGK1 in obesity-induced atrial pathology." (PMID 35998035, 2022). "In our model, obesity resulted in a marked elevation in IL-1, a cytokine frequently cited as proarrhythmic, which was prevented by SGK1 inhibition, perhaps through its effects on the NF-κB and NLRP3 axes." (PMID 35998035, 2022). "Of note, there was a marked obesity-induced atrial Il-1β expression, which was abolished with genetic inhibition of SGK1." (PMID 35998035, 2022).
Obesity (continued). "Western blotting of the p65 subunit of NF-κB revealed an obesity-related significant increase in the phosphorylated — and hence transactivated — form of the protein, which was reversed by SGK1 genetic inhibition." (PMID 35998035, 2022). "We then investigated the possibility of a dose response relating HFD/obesity with atrial SGK1 signaling, by comparing mice fed HFD for 6 weeks (which have ~50% AF inducibility) with mice fed HFD for 10 weeks." (PMID 35998035, 2022). "Beyond this, SGK1 lies downstream of a number of obesity-regulated pathways, including CHEMOKINE SIGNALING, INSULIN SIGNALING, and MAPK SIGNALING." (PMID 35998035, 2022). "SGK1 can promote the development of obesity by stimulation of the Na+ coupled glucose transporter mainly by SGLT1, which aids intestinal uptake of glucose." (PMID 33195190, 2020). "We also highlight the role of SGK1 in obesity and diabetes, and in inflammatory diseases such as endometriosis." (PMID 33195190, 2020). "SGK1 is highly expressed in human and murine hearts and is upregulated in pathophysiological settings, including obesity, heart disease and diabetes." (PMID 28086951, 2017). "SGK1 is highly expressed in the myocardium, especially in the setting of obesity and diabetes and is emerging as a contributor to cardiac fibrosis/stiffening, hypertrophy and impaired cardiac relaxation." (PMID 28086951, 2017). "SGK1 regulates the expression of a number of ion channels, including ENaC which is upregulated in tissues in the setting of obesity and diabetes." (PMID 28086951, 2017). "Genetic inhibition of SGK1 prevents obesity-induced inflammation." (PMID 35998035, 2022). "Thus, the interaction between AKT3, WNK1 and SGK1 regulates adipogenesis in vivo, and dysregulation of this pathway can lead to increased adipogenesis and obesity as well as insulin resistance." (PMID 35880040, 2022). "Overall, these data demonstrate that diet-induced obesity resulted both in increased AF inducibility, as well as an increase in SGK1 transcription, SGK1 activation through phosphorylation, and activity assayed by phosphorylation of known SGK1 targets." (PMID 35998035, 2022). "In addition to these findings, the potentially unique role of SGK1 signaling in ventricular proarrhythmia mediated by electrical remodeling presented it as an opportunistic target for treatment of obesity-related atrial arrhythmias." (PMID 35998035, 2022). "In the context of available literature, our results suggest that INa regulation may be protective in obesity-related AF, but this only partially explains the benefit derived from SGK1 genetic inhibition." (PMID 35998035, 2022). "Inflammation is thought to be involved in obesity-induced pathology (including fibrosis), and we suspected that SGK1 signaling may contribute to proinflammatory pathways in the heart." (PMID 35998035, 2022). "We sought to support our hypothesis with a comprehensive assessment of the effects of obesity on atrial gene expression and found multiple SGK1-related pathways to be upregulated, including insulin and mineralocorticoid signaling." (PMID 35998035, 2022). "SGK1 DN mouse ventricles are resistant to TAC-induced fibrosis, so we hypothesized that SGK1 inhibition may protect from obesity-induced structural remodeling in the atria." (PMID 35998035, 2022). "Based on its position downstream of metabolic pathways and its known role in electrophysiology, our a priori hypothesis was that obesity may induce pathologic SGK1 signaling." (PMID 35998035, 2022). "Genetic SGK1 inhibition alters atrial electrophysiology and prevents obesity-related AF." (PMID 35998035, 2022). "Notably, SGK1 activity seems to be required for many of these proarrhythmic pathways, suggesting a central role for this kinase in obesity-related AF, and thus making inhibition a potentially attractive target for intervention." (PMID 35998035, 2022).
Obesity (continued). "Additionally, systemic upregulation of both upstream pathways have been noted in multiple models of diet-induced obesity, positioning SGK1 as a potential key mediator of AF pathogenesis in the context of obesity." (PMID 35998035, 2022). "Importantly, the sequencing data presented here supported our preexisting hypothesis that obesity may result in activation of SGK1-related pathways, and we demonstrated increased insulin signaling, mineralocorticoid signaling, and mTOR signaling." (PMID 35998035, 2022). "The molecular mechanisms involve the regulation of key metabolic pathways and genes, such as NNAT and SGK1, highlighting ISL’s potential as a therapeutic agent for obesity and related metabolic disorders." (PMID 40004080, 2025). "PRR5L expression was found differential in visceral adipose tissue of obesity patients and found to be required for efficient mTORC2-mediated activation of SGK1 (serum/glucocorticoid regulated kinase 1)." (PMID 38483771, 2024). "Interestingly, chronic dexamethasone suppresses SGK1 in the hypothalamic arcuate nucleus, thereby increasing obesity and metabolic syndrome, indicating a significant GR effect in the hypothalamus that may be modulated by variations in pineal and local melatonin." (PMID 37970210, 2023). "We did not specifically study the effects of obesity on atrial INa (as compared with lean mice) but found that the protective effect of SGK1 inhibition in obese mice was associated with a depolarizing shift in the “window” current for INa in the atria; this may be expected to decrease late INa." (PMID 35998035, 2022). "In diabetes mellitus, excessive plasma glucose concentrations can upregulate intestinal SGK1 expression and thus SGK1-dependent stimulation of SGLT1, contributing to the maintenance of obesity." (PMID 33195190, 2020). "These obesity-induced profibrotic changes were significantly reduced in ventricular (Timp1P = 0.01; Pai1P = 0.0005) — but not atrial — tissue of SGK1 DN mice." (PMID 35998035, 2022). "Despite the protective effects of SGK1 inhibition on atrial and ventricular fibrotic signaling, detailed echocardiographic assessment of systolic and diastolic function did not reveal any notable effects of obesity or SGK1 inhibition." (PMID 35998035, 2022). "Hypothalamic SGK1 levels are increased by fasting in conditions of obesity." (PMID 32849818, 2020).
prostate carcinoma (27 papers, 2009 to 2025). A carcinoma that arises from epithelial cells of the prostate gland. "Sgk1 has been established as a gene upregulated by AR activation in both healthy and prostate cancer cells." (PMID 38303978, 2023). "Here, we demonstrated that DLEU2 regulated SGK1 expression by secluding miR-582-5p, which is involved in the pathogenesis of several types of cancer, including bladder cancer, osteosarcoma, and prostate cancer." (PMID 35075115, 2022). "Silencing SGK1 impairs prostate cancer metastasis via autophagy induction and subsequent suppression of EMT." (PMID 35317831, 2022). "In this study, we identified SGK1 as a downstream of DLEU2; the results were confirmed in prostate cancer cells and in TCGA dataset, indicating that SGK1 expression was strongly suppressed by DLEU2 knockdown." (PMID 35075115, 2022). "In prostate cancer cells, SGK1 (serum/glucocorticoid regulated kinase 1) as a tumor-promoting factor, increases migratory ability in vivo and in vitro via EMT induction." (PMID 35317831, 2022). "GSK650394 repressed androgen-mediated phosphorylation of NEDD4-2, a well-known SGK1 substrate, in LNCaP prostate cancer cells." (PMID 36457711, 2022). "RT-qPCR and western blotting indicated that SGK1 was distinctly upregulated in DLEU2-overexpressing prostate cancer cells and downregulated in DLEU2-knockdown cells." (PMID 35075115, 2022). "In prostate cancer cells, SGK1 enhanced FOXO3a accumulation in the cytosol, preventing the FOXO3a-induced transcription of autophagy-related genes." (PMID 36457711, 2022). "On the other hand, SGK1 quantity is known to be down-regulated in several tumors, such as prostate cancer, ovarian cancer, and adenomatous polyposis coli." (PMID 35625991, 2022). "Taken together, these results demonstrated that DLEU2 affected prostate cancer progression via the miR-582-5p/SGK1 axis." (PMID 35075115, 2022). "High levels of SGK1 expression have been observed in several tumors including colon cancer, prostate cancer, ovarian cancer, non-small cell lung cancer, hepatocellular carcinoma, glioblastoma multiforme, myeloma, and medulloblastoma." (PMID 35625991, 2022). "As a protein kinase, SGK1 also has elevated expression in multiple tumor types, including prostate cancer, endometrial cancer and colorectal cancer." (PMID 33093458, 2020). "In keeping with this, SGK1, SGK2, and SGK3 are rarely mutated in prostate cancer (≤0.41%), whereas amplification occurs in up to 2.5%, 2.0%, and 20.3% of cases respectively." (PMID 32630372, 2020). "The Human Protein Atlas database also shows elevated SGK-1 levels in liver cancer, colon cancer, myeloma, medulloblastoma, prostate cancer, ovarian tumors, and non-small-cell lung cancer." (PMID 33083492, 2020). "Recently, we demonstrated that ectopic expression of SGK1 significantly increased cell viability in prostate cancer cells." (PMID 33542904, 2020). "Through an in vivo tail vein metastasis assay, we also found that SGK1 downregulation significantly inhibited lung metastasis of prostate cancer cells." (PMID 33542904, 2020). "A study shows that RNA interference-mediated knockdown of SGK1 expression attenuates the androgen-mediated growth of the prostate cancer." (PMID 32070031, 2020). "Although the role of SGKs during prostate cancer is currently unclear, SGK1 over-expression has been shown to facilitate CRPC transition in a prostate cancer xenograft model, indicating that SGK1 can promote ADT-resistance." (PMID 32630372, 2020). "The increased expression of SGK1 has been found in various tumors, including prostate cancer, colorectal cancer, and non-small cell lung cancer of the squamous subtype." (PMID 32070031, 2020). "Significantly, SGK1 inhibition is reported to reduce prostate cancer cell line proliferation and invasive potential, and can synergize with the mTOR inhibitor rapamycin in vitro." (PMID 33105713, 2020).
prostate carcinoma (continued). "Radiation-induced GR expression increases the CSC population in prostate cancer through SGK1-Wnt/β-catenin signaling, thus limiting the efficacy of radiotherapy for prostate cancer treatment." (PMID 33352739, 2020). "Recently, we found that SGK1 expression is positively correlated with human prostate cancer progression and metastasis." (PMID 33542904, 2020). "In the present study, we found that SGK1 expression positively correlates with human prostate cancer (PCa) progression and metastasis." (PMID 29609629, 2018). "SGK1 is known to be up-regulated after androgen receptor activation in prostate cancer and plays an important role in androgen receptor dependent tumor proliferation and survival." (PMID 28336914, 2017). "The SGK1-antagonists that block androgen effects on LNCaP growth are considered prostate cancer therapeutics." (PMID 24864229, 2014). "The inhibition of serum glucocorticoid-regulated kinase-1 (SGK-1) has been found to decrease growth of colon and prostate cancer cells." (PMID 25485633, 2014). "GSK 650394 is a specific, competitive inhibitor of SGK-1 that was manufactured for the treatment of prostate cancer, and found to decrease growth of androgen dependent prostate cancer cells." (PMID 25485633, 2014). "Increased SGK1 expression is consistent with SGK1's role in mediating sodium retention; however, SGK1 expression is also known to enhance tumor cell survival in breast and prostate cancer cells." (PMID 19461886, 2009). "Importantly, DLEU2 knockdown significantly inhibited the growth, proliferation, and colony formation of prostate cancer cells, and these effects were partially rescued by transfection with miR-582-5p inhibitor or SGK1." (PMID 35075115, 2022). "Thus, we concluded that DLEU2 contributed to prostate cancer progression via the miR-582-5p/SGK1 axis." (PMID 35075115, 2022). "The phosphorylation of NDRG1 by SGK1 at Ser330, but not Thr346, was associated with nuclear localization, and the cytosolic form of the pNDRG1-pT346 was predominant in prostate cancer cells." (PMID 35563887, 2022). "Notably, SGK1 has been shown to be dysregulated in multiple cancers, including prostate cancer, and to participate in the regulation of tumor development." (PMID 35075115, 2022). "Although few reports have noted SGK1 reduction and its correlation with poor prognosis in adrenocortical carcinoma most studies have demonstrated that multiple types of tumors, such as colon, breast, and prostate cancer, exhibit higher levels of SGK1 expression than normal tissues." (PMID 36457711, 2022). "Notably, inhibition of miR-582-5p partially rescued the inhibitory effects of DLEU2 on SGK1 expression in prostate cancer." (PMID 35075115, 2022). "Downregulation of SGK1 expression or inhibition of its kinase activity results in antiproliferative and cytotoxic effects on various types of malignant cells, including prostate cancer cells." (PMID 34679726, 2021). "In prostate cancer, SGK1 inhibition also has anti-androgen effects." (PMID 34679726, 2021). "In recent years, an increasing number of studies have suggested that SGK1-mediated autophagy regulation plays an important role in the occurrence and progression of cancer, including glioblastoma multiforme, endometrial cancer, and prostate cancer." (PMID 33542904, 2020). "In recent years, as one of the laboratories studying the role and function of SGK1 in human cancer, we identified SGK1 as a crucial key molecule involved in prostate cancer (PCa) progression through regulation of cell apoptosis, cell cycle, invasion/migration, and autophagy." (PMID 33542904, 2020).